IDO1 (indoleamine 2,3-dioxygenase 1)
Diseases named in the same sentence as IDO1 in open-access papers (continued):
Sharing a sentence is not in itself a finding about the gene and the disease.
tumor (continued). "The catabolism of tryptophan in tumor cells mediated by IDO1 has been increasingly identified as a critical micro-environmental factor involved in aiding immune escape through suppression of anti-tumor immunity." (PMID 26378585, 2015). "Constitutive IDO1 expression is also observed in a number of human tumor lines, and is likely triggered by oncogenic events, whose characterization will be of great interest." (PMID 25691885, 2015). "Studies aimed at understanding how Bin1 restricts tumor outgrowth identified the establishment of immune tolerance through deregulation of IDO1 as a likely explanation." (PMID 26378585, 2015). "Even in malignancies, it has been shown that an increased IDO1 activity promotes the development of an immune tolerance protecting the tumor against the immune response." (PMID 26881062, 2015). "Here, the key predictive factor is most likely the presence of tumor-infiltrating lymphocytes (TILs) inside the tumor, and IDO1 is secondarily induced in response to IFNγ produced by those TILs." (PMID 25691885, 2015). "This is in line with recent findings showing that the use of IDO1 inhibitors in a mouse model barely affected the priming of new anti-tumor T-cells, but strongly reactivated effector T-cells in situ at the tumor site." (PMID 25691885, 2015). "IDO1 is expressed in tumor-infiltrating dendritic cells and in tumor stromal cells, and it has been found constitutively expressed or up-regulated in several tumor cells." (PMID 25955018, 2015). "Recent evidence in mouse models indicates that both tumor cells and host-derived cells contribute to IDO1-mediated immune resistance to anti-CTLA4 therapy." (PMID 25691885, 2015). "In fact, in animal tumor models, IDO1 inhibition by chemical or genetic interventions has been associated with the (re)activation of therapeutically relevant anticancer immune responses." (PMID 26236243, 2015). "In the mechanism proposed, IDO1 regulates the suppression of tumor-reactive effector T cells and promotes the regulation of T cell activation limiting tumor immune-surveillance and thus facilitating tumor progression." (PMID 26359356, 2015). "A number of human tumor cell lines express IDO1 in a constitutive manner, and most other tumor lines start expressing IDO1 when exposed to IFNγ." (PMID 25691885, 2015). "IDO1 was expressed by tumor cells (20% of the samples), by interstitial cells in lymphocyte-rich areas in the tumor stroma (46% of the samples), or by endothelial cells (14% of the samples)." (PMID 25691885, 2015). "There was a remarkable match between the hierarchy of our IDO1 protein expression profile per tumor type and that of the corresponding mRNA retrieved from the TCGA database." (PMID 25691885, 2015). "IDO-1 expression has been suggested to play a pivotal role in the inhibition of tumor-specific immunity." (PMID 25415278, 2014). "This IDO1-centered concept is supported by numerous preclinical studies in models of tumor immunity, autoimmunity, infection, and allergy." (PMID 25628622, 2014). "On a cellular basis, constitutive expression of IDO1 has been found in subsets of dendritic cells (DC), including DC of tumor-draining lymph nodes." (PMID 24904580, 2014). "The indoleamine 2,3-dioxygenase-1 (IDO) immunoregulatory enzyme is emerging as a key player in tumor-mediated immune tolerance." (PMID 25339948, 2014). "IDO-1 and TDO-2 induction in tumors are crucial mechanisms implicated to play pivotal roles in suppressing anti-tumor immunity." (PMID 25415278, 2014). "The expression of IDO-1 also seems to decrease the infiltration of immune cells in the tumor and increase the proportion of regulatory T lymphocytes (Tregs) in the infiltrate." (PMID 25928531, 2014). "Previous data have suggested that IDO1 inhibition can modulate immune response, delay tumor growth, and enhance dendritic cell vaccines." (PMID 24533148, 2014).
tumor (continued). "We also searched for FoxP3-positive regulatory T-cells (Tregs), since IDO-1 has been reported to increase the proportion of Tregs in the tumor infiltrate." (PMID 25928531, 2014). "The classic concept proposes that tumor cells or myeloid cells in the tumor microenvironment or draining lymph nodes express high levels of indoleamine-2,3-dioxygenase 1 (IDO1), which is the first and rate-limiting enzyme in the degradation of TRP." (PMID 25628622, 2014). "To investigate the interplay between inhibitory receptor blockade and IDO expression, we treated tumor-bearing mice with αPD-L1 or IDOi alone and harvested the tumor on the last day of therapy for analysis of IDO1 and PD-L1 transcripts by qRT-PCR." (PMID 24829760, 2014). "The findings of high IDO1 levels in several cancers and studies showing that IDO1 is critical for tumor survival has led to intense interest in the potential of anti-IDO1 based immunomodulatory therapeutics." (PMID 23671415, 2013). "IDO1 is also expressed by a variety of tumours and by antigen-presenting cells (APC), including macrophages, human monocyte-derived DC, and individual subsets of murine DC." (PMID 23973990, 2013). "The interplay between COX-2 and IDO1 is further underpinned by studies in animal models of cancer, where pharmacological blockade of COX-2 translated into down-regulation of IDO1 expression at the tumour site, leading to decreased serum kynurenines." (PMID 23973990, 2013). "IDO1 inhibitors, such as the small molecule inhibitor, 1MT, have shown anti-tumor potential in combination with conventional chemotherapeutic drugs." (PMID 23671415, 2013). "Further, in these samples, normal adjacent tissue showed lower RPMS1 expression and lower IDO1 expression compared to their tumor counterparts." (PMID 23671415, 2013). "In 191 cases (72%), epithelial IDO1 positivity was found in both the invasion front and the centre of the tumour." (PMID 22108515, 2012). "Our expectation was that if differences in Ido1+ and Ido1− tumor growth are immune modulated, then both tumors should grow similarly in SCID/beige mice." (PMID 22654951, 2012). "Activation of Ido1 by IFN-γ links inflammation and cancer immune surveillance, and an increase in IFN-γ within the tumor microenvironment also induced IDO1 expression in APCs and DCs that localize to the tumor-draining lymph nodes." (PMID 22654951, 2012). "IDO1 expression in tumor cell lines and primary tumor cells is mainly triggered by IFN-γ and translates into tryptophan degradation into immune suppressive metabolites, collectively referred to as kynurenines." (PMID 22567028, 2012). "Seventy-one percent of patients with IDO1-low primary tumours were free of metastasis, whereas this was the case for only 50% of patients with IDO1-high primary tumours." (PMID 22108515, 2012). "Ido1 is expressed by tumor cells; however, the level of Ido1 expression is significantly lower than in placenta." (PMID 22654951, 2012). "Cell cycle distributions within Ido1− and Ido1+ tumor cell populations also differ in that Ido1+ cells show a higher proportion of cells in S and M phases than Ido1− cells." (PMID 22654951, 2012). "Tumor cell inhibition of immune response was only demonstrated for Ido1-transfected clones, exhibiting 1000-fold increased expression of Ido1 mRNA relative to placental levels." (PMID 22654951, 2012). "In this study, we examined the impact of IDO1 on tumor growth and metastasis in immune-competent and immune-deficient mice." (PMID 22654951, 2012). "Initially, we measured Ido1 expression in a panel of mouse tumor cell lines of differing histological origin." (PMID 22654951, 2012). "Analysis of IDO1 expression at the tumour invasion front can be of additional value in the therapeutic decision-making process of pN1-staged patients." (PMID 22108515, 2012).
tumor (continued). "We first analyzed the impact of Ido1 expression on tumor growth and spontaneous pulmonary metastasis formation and then investigated the IDO1-regulated mechanisms involved in tumorigenesis." (PMID 22654951, 2012). "By analysing the distribution of the IDO1 scores at the tumour invasion front, we found that a large majority of patients with a mean score higher than 1.9 had a short survival." (PMID 22108515, 2012). "The involvement of IDO1 in cell cycle regulation and tumor cell stress response, in addition to the known role of IDO1 in tumor immunosuppression, make it an attractive target for antitumor therapy." (PMID 22654951, 2012). "In a small subset of samples, double immunostainings for IDO1 and CD3 were performed, revealing a significantly higher proportion of intratumoural CD3+ cells in IDO1-low expressing tumours as compared with IDO1-high expressing tissue samples." (PMID 22108515, 2012). "Higher IDO1 expression at the tumour invasion front was an independent adverse prognostic factor in pT1-4N1Mx-staged CRC." (PMID 22108515, 2012). "Taken together, these results indicate that Ido1 plays role in tumor growth and metastasis formation." (PMID 22654951, 2012). "For the first time, we showed that Ido1 regulates tumor metastasis via immunosuppressive mechanisms." (PMID 22654951, 2012). "A total of 13 cases (5%) were IDO1 positive in the invasion front only; 30 cases (11%) were IDO1 positive in the tumour centre only." (PMID 22108515, 2012). "The clone the of the 4T1 tumor cells with the highest Ido1 expression was transfected with Ido1 siRNA and a control vector to generate stable 4T1/Ido1− and 4T1/vector clones." (PMID 22654951, 2012). "We demonstrated that IDO1 is involved in the regulation of tumor cell proliferation in vitro and in vivo." (PMID 22654951, 2012). "The differences in Ido1+ and Ido1− tumor growth in immunodeficient mice indicate a possible role of Ido1 in apoptosis and tumor cell proliferation." (PMID 22654951, 2012). "Ido1 activation occurs commonly in tumor cells and/or tumor-draining lymph nodes (TDLNs), and pharmacological inhibition of IDO1 with 1-MT has been shown to result in T-cell-dependent antitumor responses in animal models." (PMID 22654951, 2012). "To further elucidate the role of IDO1, in tumor growth and metastasis formation, we used NT-5/Ido1− cells and NT-5/Ido1+ tumor cells and FVB/N mice that are immunocompetent for NT-5 cells." (PMID 22654951, 2012). "Despite the bulk of evidence supporting a role for IDO in promoting tumor formation and tumor immune escape, there have been studies showing an anti-tumor activity of IDO1." (PMID 21625531, 2011). "In both tumor-draining lymph nodes and tumors, IDO1 creates local tolerance by directly suppressing T-cell responses and enhancing immunosuppression mediated by regulatory T cells (Treg)." (PMID 21625531, 2011). "Although 1-L-MT was shown to more effectively inhibit IDO1 in enzyme assays and in cancer cell lines, 1-D-MT showed superior anti-tumor activity in mouse models and was therefore chosen for clinical trials." (PMID 21625531, 2011). "Immune infiltration analysis suggested that GSK3B and IDO1 may influence the tumour immune microenvironment." (PMID 42220063, 2026). "Therefore, the study proposes a novel therapeutic strategy: IFN-γ combined with IDO1 or AhR inhibitor can disrupt the dormancy of TRCs and induce their apoptosis, thus achieving more effective tumor clearance." (PMID 41438587, 2026). "Consequently, IDO1 inhibitors enhance anti-tumor immunity and show strong synergy when combined with immune checkpoint blockade." (PMID 41602107, 2026). "Combined with ultrasound therapy, the HB-NLG8189@MPCM group significantly elevated Th cell and CTL populations in tumors while suppressing IDO-1 activation and modulating regulatory T cell infiltration, thereby reversing the immunosuppressive tumor microenvironment." (PMID 41451226, 2025).
tumor (continued). "Another study indicated that IDO1 inhibition led to aberrant expression of IFN‐γ and microphthalmia‐associated transcription factor, dampening T‐cell‐mediated antitumor responses and promoting tumor survival." (PMID 41332472, 2025). "In addition, IDO1 contributes to cancer development by promoting neovascularization and production of the pro-inflammatory cytokine IL-6, which leads to tumor immune escape." (PMID 40332338, 2025). "The massive amount of indoleamine 2,3‐dioxygenase 1 (IDO‐1) in tumor cells and tumor‐associated immune cells forms a feedback loop that maintains immunosuppressive tumor microenvironment (ITM) and causes immune escape, resulting in the poor prognosis of platinum chemotherapeutics." (PMID 39887941, 2025). "IDO1 is highly expressed in various immune cells, fibroblasts, and tumor cells." (PMID 41035912, 2025). "Tumor cells may compensate for IDO1 inhibition by upregulating TDO2, maintaining kynurenine production." (PMID 41562065, 2025). "Previous research has indicated that IL‐6 upregulates and sustains IDO1 expression in tumor cells, implying that IDO1 may act differently in response to identical signaling stimuli across different cell types." (PMID 40103267, 2025). "Moreover, the inhibition of IDO-1 activity by 1-MT, coupled with in situ-generated nitric oxide, normalizes tumor vasculature, reprogramming the immunosuppressive TME into an immunostimulatory phenotype." (PMID 40169560, 2025). "In many tumours, IDO1 is highly expressed, AhR levels are also elevated." (PMID 40040508, 2025). "Thus, IDO1 is considered a tumor immune checkpoint, and the efficacy of IDO1 inhibitors, alone or in combination with other drugs (e.g., immune checkpoint inhibitors), has been extensively studied in cancer immunotherapy." (PMID 40715093, 2025). "Additionally, HPV-positive tumor cells presented increased expression of immune-related proteins, including IDO1 and HLA-DR, which is consistent with the viral origin of these tumors and previous reports of enriched interferon signaling." (PMID 41254766, 2025). "The inconsistent behavior between TRCs and regular tumors may be due to the differential expression patterns of IDO1 and AhR in tumor stem cells." (PMID 40103267, 2025). "IDO1 has been reported to be expressed in both tumor and stromal cells." (PMID 40287406, 2025). "Similarly, although targeted inhibition of amino acid metabolism can reduce the release of immunosuppressive molecules such as ARG1, NO, and IDO1 in MDSCs and improve the tumor immunosuppressive microenvironment." (PMID 39990210, 2025). "Moreover, the observations highlighted in this article underscore the importance of further investigating the role of IDO1 in future studies, not only as a marker in tumor cells but also within the context of the tumor microenvironment." (PMID 40287406, 2025). "The autocrine COX‐2/PGE2 pathway persistently activates IDO1, which might partially explain its role in promoting dormancy in tumor cells." (PMID 40103267, 2025). "The inverse trend observed in our serum data may suggest that IDO-1 activity is largely confined to the tumor microenvironment, limiting its systemic release, or that compensatory immune mechanisms reduce circulating IDO-1 levels in LC patients." (PMID 41007708, 2025). "IDO1-mediated kynurenine accumulation has been shown to suppress dendritic cell maturation and impair antigen presentation, leading to reduced activation of tumor-infiltrating lymphocytes (TILs)." (PMID 40917745, 2025). "Thus, the IDO1/TDO2–kynurenine axis serves as a metabolic immune checkpoint that promotes tumor immune escape." (PMID 41562065, 2025). "Thus, the mere catalytic inhibition of the IDO1 enzyme results in ineffectiveness for targeting the tumor growth in the TME because of the additional signaling function of the IDO1 protein in the tumor." (PMID 41262240, 2025).
tumor (continued). "This indicates that cisplatin not only acts via the known cytotoxic effect, but may induce a reduction in tumor-supporting proteins, like IL-6 and IDO1, by MSCs in the tumor microenvironment at subtoxic concentrations." (PMID 40699630, 2025). "The central role of IDO1 in tumor immune evasion has spurred development of multiple pharmacological inhibitors, including epacadostat (INCB024360) and indoximod (1-methyl-D-tryptophan), which have shown promising preclinical efficacy in combination with PD-1/PD-L1 blockade." (PMID 40894232, 2025). "Indoleamine 2,3-dioxygenase 1 (IDO1) was found at the plasma membrane level of various tumor cells." (PMID 40699758, 2025). "Additionally, keywords like “inhibitors” and “IDO1” experienced marked increases in burst strength between 2019 and 2022, a trend likely driven by the rapid advancements in tumor immunotherapy." (PMID 40666095, 2025). "IDO1 is immunosuppressive and tumor-stimulating and is secreted, among others, by MSCs." (PMID 40699630, 2025). "This putative contradiction could be explained by different hypotheses, that support a possible positive role of IDO-1 in the tumor immune response: the IDO-1-induced tryptophane deprivation has been reported to also decrease tumor cell proliferation." (PMID 40475772, 2025). "Here, we extended the pro-tumorigenic adverse effect of IDO1 catalytic inhibition to different human IDO1-expressing tumor cell lines, dissecting the signaling pathway mediated by IDO1 and proposing IDO1 protein degradation as an effective approach to neutralize the dual function of IDO1 in cancer." (PMID 41262240, 2025). "Moreover, the IDO1/TDO–Kyn–AHR–AQP4 signaling axis, together with AQP4’s interaction with tumor-associated immune components such as macrophages, warrant the exploration of combined therapeutic approaches." (PMID 41324079, 2025). "Consequently, sustained activation of this IDO1/Kyn/AhR pathway potently facilitates tumour immune escape." (PMID 41275427, 2025). "Thus, the intrinsic effect exerted by IDO1 catalytic inhibitors in the tumor cell represents an adverse “on-target” effect that promotes, rather than inhibits, the tumor growth." (PMID 41262240, 2025). "Indoleamine 2,3-dioxygenase 1 (IDO1), a heme-containing oxidoreductase that catalyzes tryptophan catabolism to kynurenine in the first rate-limiting step of the kynurenine pathway, plays an important role in tumor evasion of immune surveillance." (PMID 40572474, 2025). "IDO1 plays a crucial role in tryptophan metabolism and immune suppression, suggesting that inhibiting this key factor could effectively control tumor development." (PMID 40909948, 2025). "However, in the TME, tumor cells, stromal cells, or myeloid-derived suppressor cells (MDSCs) highly express indoleamine 2,3-dioxygenase (IDO1) or tryptophan 2,3-dioxygenase (TDO)." (PMID 41293169, 2025). "Reasons for this failure may range from differences in the patient cohort to incomplete inhibition calling for a better understanding of the complex function and regulation of IDO1 in the tumor and its microenvironment (TME)." (PMID 39962447, 2025). "This pro-cancer effect may predominantly exist and widely contribute to the poor tumor prognosis, considering the high T-cell infiltration and IDO1 expression levels in GBM cells." (PMID 39863603, 2025). "Most researchers agree that IDO1 inhibition may synergize well with ICIs, potentially leading to improved anti-tumor outcomes." (PMID 39997327, 2025). "Suppressed IDO1 activity in the tumor microenvironment might be directly inhibited by AF1q at the transcriptional level or by enhancing anti‐tumor immunity and reducing immune suppression." (PMID 40062505, 2025). "By suppressing antitumor immune responses, high IDO1 expression facilitates tumor progression, indicating that combining IDO1 inhibitors with immunotherapy may offer a promising strategy for cancer treatment." (PMID 41332472, 2025).